IL10 (interleukin 10)
Diseases named in the same sentence as IL10 in open-access papers (continued):
Sharing a sentence is not in itself a finding about the gene and the disease.
Opportunistic infection (9 papers, 2006 to 2022). An infection that is caused by a pathogen that would generally not be able to cause an infection in a host with a normal immune system. "Very recently, IL-10-producing NK cells have been found in the spleen after haemorrhagic shock and are associated with impaired immune defence against opportunistic infections." (PMID 25609031, 2015). "The up-regulation of the sera IL-10 level suggested a higher chance of disease persistence or secondary opportunistic infection in P(H1N1) infection." (PMID 22174866, 2011). "Elevated levels of inflammatory biomarkers including IL-6, IL-10, and tumor necrosis factor (TNF)-α were observed in patients with opportunistic infections in the 2DR arm at baseline." (PMID 34983415, 2022). "Elevated levels of IL-10 in serum during advanced HIV infection may enhance immune suppression, allowing for opportunistic infections." (PMID 22164280, 2011). "Elevated levels of IL-10 in serum during advanced HIV infection may enhance immune suppression, allowing opportunistic infections." (PMID 16504020, 2006). "Additionally, a recent study on Toxoplasma infection revealed that the absence of PD-1 signaling promotes an increase in IL-10 production by CD4+ and CD8+ T cells, which increases the susceptibility to other opportunistic infections." (PMID 35812458, 2022).
polyp (9 papers, 2009 to 2024). A usually exophytic mass attached to the underlying tissue by a broad base or a thin stalk. "Nasal polyp samples revealed few to moderate positive IL-10 structures in epithelium and moderate number of positive structures in connective tissue." (PMID 34208325, 2021). "We observed that, as compared with healthy subjects, the IL-10 expression in peripheral DC was significantly lower in polyp patients." (PMID 28388587, 2017). "Expressions of IFN-γ, IL-5, IL-17A, IL-25 and IL-10 were significantly higher in the 3 months and 6 months murine polyp model than in the control mice." (PMID 27584662, 2016). "The anti-inflammatory nature of IL-10 also contributes to polyp formation by enhancing local Th2 inflammation and the associated tissue damage." (PMID 25133733, 2014). "Other groups have demonstrated a higher release of IL-5 and IL-10 in polyp tissue than in turbinate tissue from healthy controls." (PMID 25133733, 2014). "As compared with healthy controls, the IL-10 levels in DCs were significantly lower in polyp group." (PMID 28388587, 2017). "In addition, further studies are needed to determine whether IL-10 can be used to indicate poor surgical outcome or increased polyp recurrence." (PMID 27584662, 2016).
psoriasis vulgaris (9 papers, 2016 to 2025). Plaque psoriasis is the most common presentation of psoriasis. "Meta-analysis of the results for all markers, including IFN-γ, IL-4, IL-17, IL-23, IL-6, TNF-α, and IL-10, for subjects with psoriasis vulgaris of blood-heat syndrome revealed significant between-study heterogeneity (I2 > 75%) with random-effects modeling." (PMID 27274756, 2016). "The pooled analyses suggest that levels of IFN-γ, IL-17, IL-23, and TNF-α are significantly elevated and that levels of IL-4 and IL-10 are significantly decreased in sera of patients with psoriasis vulgaris of blood-heat syndrome." (PMID 27274756, 2016). "Studies found that the increased Th2 and Th17 immune response may play a role in EP pathogenesis, endorsed by the higher serum level of interleukin (IL)-13, IL-4, IL-6 and IL-10 in EP patients than patients with plaque psoriasis." (PMID 34970217, 2021). "Thus, we detected the expression of ICOS, PD-1, HLA-DR, and Ki-67 on cTfh cells and secretion of IL-21, IL-17, IFN-γ, and IL-10 by cTfh cells in patients with psoriasis vulgaris." (PMID 27774460, 2016). "We performed a systematic review and meta-analysis to determine whether seven well-known immunological serum markers (IFN-γ, IL-4, IL-17, IL-23, IL-6, TNF-α, and IL-10) are elevated or decreased in patients with psoriasis vulgaris of blood-heat syndrome compared with controls." (PMID 27274756, 2016). "A study showed that patients with blood-heat syndrome of psoriasis vulgaris had substantially elevated levels of interferon-gamma, IL-17, IL-23, and TNF-α and significantly decreased levels of IL-4 and IL-10." (PMID 32843084, 2020). "In summary, patients with psoriasis vulgaris of blood-heat syndrome show significantly elevated levels of IFN-γ, IL-17, IL-23, and TNF-α and decreased levels of IL-4 and IL-10." (PMID 27274756, 2016).
scleroderma (9 papers, 2015 to 2024). Scleroderma is a rare autoimmune connective tissue disorder characterized by abnormal hardening of the skin and, sometimes, other organs. "In a bleomycin-induced scleroderma model, IL-6 deficiency in B cells can reduce skin fibrosis, while IL-10 deficiency in B cells can increase skin fibrosis." (PMID 39080112, 2024). "Interestingly, a study using a bleomycin-induced model of scleroderma highlighted how B cell-specific IL-6 deficient mice had attenuated skin and lung fibrosis whilst B cell-specific IL-10-deficient mice had more severe fibrosis." (PMID 36726987, 2022). "We have not been able to show restored capacity of B cells to produce IL-10 by addition of 500 ng/mL BAFF-Fc-Chimera opposed to previous research performed in scleroderma, where BAFF inhibition restored B-eff/B-reg imbalances in mice." (PMID 36253785, 2022). "Moreover, IL-10+ Bregs found in the skin play a crucial role in mitigating inflammation and fibrosis in scleroderma, both in skin and lymphoid tissues." (PMID 38426103, 2024). "Additionally, in a mouse scleroderma model, IL-6+ effector B cells exacerbate the disease, while IL-10+ regulatory B cells provide protection." (PMID 38426103, 2024). "The beneficial effects observed for 8% pirfenidone gel on localized scleroderma plaques may be related to its reported capacity to inhibit proinflammatory cytokines levels, as well as to activate interleukin 10 (IL-10) production." (PMID 25533576, 2015). "In addition, BAFF antagonists reduce skin and pulmonary fibrosis in scleroderma models by reducing IL-6+ Beffs rather than IL-10+ Bregs." (PMID 39080112, 2024). "We found that HUMSCs-Ex elevated M1 macrophage markers (IL-6, IL-12p40, iNOS) and inhibited M2 macrophage markers (IL-4, IL-10, Arg-1 and CD206) in a mouse model of scleroderma, thus suggesting that HUMSCs-Ex might play an antifibrotic role by regulating the M1/M2 macrophage balance." (PMID 34784013, 2022).
scrub typhus (9 papers, 2012 to 2025). Scrub typhus is a rare dust mite-borne infectious disease caused by the Orientia tsutsugamushi bacterium and characterized clinically by an eruptive fever which is potentially serious. "It was reported that some cytokines, including IL-8, contribute to disease severity in patients with scrub typhus, and cytokines such as IL-6 and IL-10 were associated with the development of AKI." (PMID 28419138, 2017). "In the present study scrub typhus patients had significantly higher levels of IL-10 than infectious disease controls, and high IL-10 levels showed some association with mortality." (PMID 24516677, 2014). "Overproduction of IL-10 appears to be linked to disease severity, but in cases with low serum levels IL-10 conferred protection in patients with scrub typhus." (PMID 35925895, 2022). "Enhanced expression of IL-10 by O. tsutsugamushi infection is consistent in in vitro and in vivo experiments, as well as studies in scrub typhus patients." (PMID 30233599, 2018). "Plasma levels of IL-6, IL-8 and, particularly IL-10, were markedly higher in patients with scrub typhus than in those with murine typhus." (PMID 22192733, 2012). "Increase of IL-10 was found previously in scrub typhus patients as well." (PMID 29760694, 2018). "Previous studies have shown increased plasma or serum levels of various cytokines in scrub typhus patients such as TNFα, IFNγ, IL-6 and IL-10, but these studies included a rather low number of patients (n = 9–55) and relatively few inflammatory mediators were examined." (PMID 24516677, 2014). "We propose that the type I IFNs/IL-10 axis might play a critical role in suppressing the cellular immunity during acute phase infection, as well as the short longevity of T cell responses, often observed in scrub typhus patients." (PMID 30233599, 2018). "Several inflammatory cytokines such as TNFα are potent inducers of IL-10, and whether high IL-10 levels in scrub typhus patients reflects the degree of inflammatory stimuli as a counteracting mechanism or whether high IL-10 could attenuate microbe killing is at present unclear." (PMID 24516677, 2014). "Murine cytokine expression data revealed that the two most virulent strains, Ikeda and Kato, induced higher levels of IL-6, IL-10, IFN-γ and MCP-1 than other strains, consistent with increased levels of these cytokines in patients with severe scrub typhus." (PMID 40587585, 2025). "Therefore, induction of the type I IFN/IL-10 axis by O. tsutsugamushi infection might play a significant role in the suppression of T cell responses and contribute to the short longevity of cell-mediated immunity, often observed in scrub typhus patients." (PMID 30233599, 2018). "Furthermore, IL-10 can attenuate activation of the coagulation system, inhibit cytokine release, and potently modulate the fibrinolytic system, resulting in an inhibition of procoagulant responses in humans with induced endotoxaemia, thus raising further questions regarding its role in scrub typhus." (PMID 22192733, 2012). "High levels of several cytokines, including IL-6, IL-8, IL-10, monocyte chemoattractant protein-1 (MCP-1), macrophage inflammatory protein-1 beta (MIP-1β), IFN-γ and TNF were reported during the acute phase of scrub typhus patients, and correlated with disease severity." (PMID 35925895, 2022).
sickle cell anemia (9 papers, 2009 to 2025). "Plasma concentrations of the pro-inflammatory cytokines TNF-α and IL-1β, the adhesion molecule sICAM-1 and the anti-inflammatory cytokine IL-10 were measured in a total of 55 adult subjects with sickle cell disease and 17 haemoglobin AA controls." (PMID 23922670, 2013). "After adjustment for hydroxyurea therapy by analysis of variance, patients with sickle cell disease had higher plasma interleukin-8, interleukin-10, and VEGF concentrations compared to the control participants and lower plasma RANTES concentrations." (PMID 19956689, 2009). "In the present study, we observed higher plasma levels of interleukin-8 and interleukin-10 in sickle cell disease patients compared to control subjects." (PMID 19956689, 2009). "On the other hand, in sickle cell anemia, iron overload suppresses IL-10, which may contribute to the production of free radicals." (PMID 30836628, 2019). "The levels of the Th2 type cytokines IL-4, IL-10 and IL-13 are relatively enhanced whereas IFN-γ responses are compromised in thalassemia, sickle cell disease (SCD) and autoimmune hemolytic anemia." (PMID 23358441, 2013). "In light of such observations and the comparability of IL-10 concentration between SSn and SSu in the present study, it seems possible that there may be an imbalance between the expression of inflammatory and anti-inflammatory immune responses in sickle cell disease subjects with chronic leg ulcers." (PMID 23922670, 2013). "Plasma concentrations of interleukin-8, interleukin-10 and VEGF were elevated in the patients with sickle cell disease compared to controls (P≤0.003)." (PMID 19956689, 2009). "On the other hand, sickle cell anemia patients with iron overload, defined by elevated serum ferritin of >2247 pmol/L, had lower serum IL-10 levels compared to non-iron-overloaded patients." (PMID 26646112, 2015).
sleep disorder (9 papers, 2017 to 2025). A change from the patient's baseline sleeping pattern, in the hours slept and/or an alteration/dysfunction in the stages of sleep. "Previous studies have also reported elevated levels of IL-2 and IL-1β upon improved sleep and an elevation in IL-10 levels upon sleep disorders." (PMID 37139438, 2023). "In this study, the concentrations of IL-6, TNF-α, and IL-10 were monitored before and after operation in patients with sleep disorders at different time points, to observe the relationship between sleep disorders and the level of cytokines." (PMID 36570021, 2022). "IL-10 and IL-1 are both increased with either sleep deprivation or sleep disturbances, again consistent with our findings." (PMID 33598780, 2021). "Regarding the mechanisms of sleep disorders in JIA children, previous research has suggested that JIA patients exhibit a significant inflammatory response, including a decrease in IL-10 and an increase in pro-inflammatory cytokines." (PMID 41561497, 2025).
tetanus (9 papers, 2010 to 2024). A serious infectious disorder that follows wound contamination by the Gram-positive bacterium Clostridium tetani. "Type 1 (IFN-γ) and regulatory (IL-10) cytokines were dominant in the response to cCFP; following tetanus immunisation, type 2 cytokines were more prominent." (PMID 21040693, 2010). "As determined by receiver operating characteristic (ROC) curve analysis, tetanus-specific IL-10 spots at baseline had the highest predictive value (p = 0.005) for tumor burden at month 6, with an area under the curve (AUC) of 0.90 (sensitivity 100%, specificity 78%)." (PMID 38473247, 2024). "Atopy was also associated with greater IL‐10 responses to antigens (median values: cockroach, 64 vs. 38; dust mite, 432 vs. 304; tetanus 172 vs. 133 pg/mL) but not PHA." (PMID 27042305, 2016). "Furthermore, Satoguina and collaborators showed tetanus-specific regulatory T cells clone producing high levels of IL-10 and TGF-β induced the production of IgG4 by naive and memory B cells in a GITR/GITRL-, TGF-β-, and IL-10-dependent manners." (PMID 24137161, 2013). "The production of 9 cytokines (IFN-γ, TNF-α, IL-2, IL-4, IL-10, IL-17, IL-21, TGF-β, GM-CSF) following in vitro stimulation of PBMCs with tetanus and diphtheria toxoid was analyzed, and was found to be similar in young and elderly adults." (PMID 27602049, 2016). "The proportion of children for whom positive responses to cCFP, antigen 85 and tetanus toxoid were detected varied by cytokine: for cCFP, 86%, 48%, 71% and 90% of infants had positive responses to IFN-γ, IL-5, IL-13 and IL-10, respectively." (PMID 23236367, 2012).
Tinnitus (9 papers, 2020 to 2025). Tinnitus is an auditory perception that can be described as the experience of sound, in the ear or in the head, in the absence of external acoustic stimulation. "IL-10, an anti-inflammatory cytokine, was lower in patients with tinnitus than in the control group, and decreased as the duration of tinnitus increased." (PMID 34205595, 2021). "Interestingly, IL-10 levels increased with the chronicization of tinnitus, while levels of IL-1α, IL-1β, IL-2, IFN-γ, TNF-α, and Transforming Growth Factor (TGF)-β remained unchanged." (PMID 40697272, 2025). "In this study, significantly lower levels of IL-10 were found in patients with tinnitus, but not in those with hearing loss." (PMID 40558411, 2025). "The level of interleukin 10, an anti-inflammatory cytokine also known as human cytokine synthesis inhibitory factor, was lower in people with tinnitus, but not in people who had hearing loss without tinnitus." (PMID 33154715, 2020). "For instance, IL-1β was found in 30 patients with chronic tinnitus to correlate with distress levels, as well as tinnitus awareness, and IL-10 was found lower in subjects with tinnitus when compared to those without tinnitus (n = 114)." (PMID 38079022, 2023). "While our panels did not include proteins such as IL-1β or BDNF, our analysis suggest that IL-10 plays no role in constant tinnitus." (PMID 38079022, 2023). "In chronic tinnitus sufferers, a relaxation training program can result in significantly decreased stress, anxious depression, anger, and tinnitus disturbance, paralleled by a reduction of TNF-a, but not IL-6 or IL-10." (PMID 38027533, 2023).
acute alcoholic hepatitis (8 papers, 2011 to 2025). "The decreased IL-10 production in 4-1BB+ T lymphocytes may again support that 4-1BB expression reflects activated T lymphocytes also in alcoholic hepatitis." (PMID 34352016, 2021). "Indeed, LPS induces an anti-inflammatory state in monocytes from patients with acute alcoholic hepatitis, including increased IL-10 production, induction of PD1 and TIM3 and suppression of T cell responses." (PMID 31507587, 2019). "A recent study indicated that cytokines such as tumor necrosis factor-alpha and interleukin-10 in adipose tissues of acute alcoholic hepatitis patients were elevated, and were correlated with the serum CRP concentration, implying that inflammation caused the production of CRP." (PMID 21806828, 2011). "Exosomes mediate the communication between alcohol-treated hepatocytes and immune cells, and the levels of miR-27a in exosomes and inflammatory cytokines, such as interleukin 10 (IL-10) and TGF-β, are higher in alcohol-treated mice and patients with alcoholic hepatitis." (PMID 28025544, 2016). "In patients with acute alcoholic hepatitis, blocking PD-1 and TIM-3 could reverse T-cell production of IFN-γ, reduce the numbers of interleukin 10-producing T cells, and increase antibacterial immune responses impaired in this condition." (PMID 27034168, 2016).
African trypanosomiasis (8 papers, 2012 to 2023). "However, the in vivo cellular source of IL-10 and the window within which these cells exert their function during the course of African trypanosomiasis, as well as the associated molecular mechanism(s) implicated in its production, remain poorly understood." (PMID 32012211, 2020). "On the other hand, IL-10 is an anti-inflammatory cytokine, acting as a master regulator of inflammation during both African trypanosomiasis and other diseases." (PMID 35464430, 2022). "Here, we aimed at refining the cellular contribution of IL-10 during experimental African trypanosomiasis using the T. congolense model in C57BL/6 mice." (PMID 32012211, 2020). "Obviously, in the absence of IL-27 signaling, excessive secretions of IFN-γ by CD4+ T cells also mediate liver pathology and mortality, although IL-10 signaling still fully functions and the infected mice produce even more IL-10, in African trypanosomiasis." (PMID 26222157, 2015). "In this respect, IL-10 has been found to be essential for maintenance of the immunological balance between protective and pathological immune responses during African trypanosomiasis." (PMID 26222157, 2015). "IL-10 signaling has been previously suggested to be involved in maintaining this immunological balance in African trypanosomiasis." (PMID 26222157, 2015). "Together, this review aims at summarizing the current knowledge on the opposite immunopathological molecular “Yin-Yang” switch roles of MIF and IL-10 in the modulation of the host immune microenvironment during infection, and more particularly during African trypanosomiasis as a paradigm." (PMID 35464430, 2022). "However, the cellular source of IL-10 in vivo and the window within which these cells exert their function during the course of African trypanosomiasis remain poorly understood, which hampers the design of effective therapeutic strategies." (PMID 32012211, 2020). "Strikingly, infected wild-type mice treated with anti-IL-10R mAb survived significantly shorter than infected IL-27R-/- mice (p<0.01), suggesting that IL-27 and IL-10 may independently regulate inflammatory responses during African trypanosomiasis." (PMID 26222157, 2015). "Thus, both IL-10 signaling and IL-27 signaling are required for survival of mice infected with the parasites via preventing aberrant inflammatory responses, although they function in a distinct manner in African trypanosomiasis." (PMID 26222157, 2015). "Thus, our results do not support the proposal that Treg-derived IL-10 contributes to enhanced-resistance to experimental African trypanosomiasis." (PMID 22860150, 2012).